PDLIM2 (PDZ and LIM domain 2)
Diseases named in the same sentence as PDLIM2 in open-access papers (continued):
Sharing a sentence is not in itself a finding about the gene and the disease.
breast carcinoma (continued). "Suppression of PDLIM2 in invasive PRAD (DU145) and breast cancer cells (MDA-MB-231) causes increased E-cadherin expression and cell–cell contact, loss of directional migration, altered expression and activity of many transcription factors associated with tumorigenesis, and reversal of EMT." (PMID 35707002, 2022). "Moreover, high PDLIM2 expression with M2 macrophage enrichment is more evident in the stroma of TNBC than in other breast cancer subtypes." (PMID 36531051, 2022). "We conclude that PDLIM2 influences the activity of this population of macrophages in breast cancer." (PMID 36531051, 2022). "It will be interesting to further investigate whether PDLIM2 expression in breast cancer M2 macrophages can influence tumour immunity or therapy responses." (PMID 36531051, 2022). "Overall, these analyses support the role of PDLIM2 in the recruitment and differentiation of M2 macrophages in the breast cancer tumour environment and suggest that PDLIM2 expression contributes to the function of M2 TAMs in the progression of breast cancer, particularly TNBC." (PMID 36531051, 2022). "Breast cancer cases were stratified for PDLIM2 mRNA expression into low, moderate, or high expression for analysis with the CIBERSORT-Absolute mode, which generates a score that quantitatively reflects the overall abundance of each cell type from a bulk mixture." (PMID 36531051, 2022). "Since, M2 macrophage infiltration may contribute to the aggressiveness of breast cancer, we were interested to further test the relationship between PDLIM2 expression and M2 macrophage infiltration by analysing publicly available datasets for breast cancer." (PMID 36531051, 2022). "However, it has not been established whether there is a clinical consequence of high PDLIM2 expression in TNBC or other breast cancers." (PMID 36531051, 2022). "We conclude that PDLIM2 expression influences the tumour associated stroma and, in particular, M2 macrophage infiltration that may contribute to the progression of TNBC or other subsets of breast cancer." (PMID 36531051, 2022). "In contrast, reduction of Pdlim2 expression failed to negatively impact the growth of liver-aggressive breast cancer cells in soft agar, suggesting that this candidate was not important for Claudin-2-mediated anchorage-independent growth." (PMID 30692208, 2019).
hepatocellular carcinoma (6 papers, 2022 to 2025). A malignant tumor that arises from hepatocytes. "Especially in hepatocellular carcinoma (HCC), Jiang and colleagues illustrated a reduction in PDLIM2 expression in both tissue samples and cells, which was associated with an unfavorable prognosis for individuals diagnosed with HCC." (PMID 38992675, 2024). "In hepatocellular carcinoma, PDLIM2 functions as a tumor suppressor by negatively regulating β-catenin." (PMID 38880883, 2024). "PDLIM2 negatively regulates β-catenin to prevent malignant phenotypes in hepatocellular carcinoma cells." (PMID 34713769, 2022). "OTUD6B suppressed hepatocellular carcinoma metastasis, involving a feedback loop consisting of OTUD6B, pVHL, and HIF-1α; CircPTPN12 bolstered the assembly of the PDLIM2/OTUD6B complex and inhibited hepatocellular carcinoma progression by PDLIM2/NF-κB pathway." (PMID 40651961, 2025).
ovarian carcinoma (6 papers, 2016 to 2025). A malignant neoplasm originating from the surface ovarian epithelium. "Via NO synthesis inhibition, we demonstrated PDLIM2-deficient ovarian cancer cells grow in a NO-dependent manner." (PMID 26593252, 2016). "Next, we investigated the underlying mechanism of PDLIM2 repression in ovarian cancer, and asssessed the potential role of DNA methylation, a major mechanism responsible for tumor suppressor gene suppression in malignant cells." (PMID 26593252, 2016). "PDLIM2 expression is also downregulated in ovarian cancer tissues and cells leading to increased malignant biological behaviors (i.e., proliferation, migration, and invasion)." (PMID 40476213, 2025). "In ovarian cancer, downregulation of PDLIM2 promotes tumor growth by modulating NOS2-derived nitric oxide signaling and the recruiting M2 type macrophages." (PMID 38880883, 2024). "In ovarian cancer (OV), PDLIM2 is epigenetically suppressed, and PDLIM2 inhibition promotes OV growth in vivo and in vitro via NOS2-derived nitric oxide signaling, leading to M2-type macrophage recruitment." (PMID 37894409, 2023). "Correlation analysis demonstrated tumor expression of NOS2 is negatively correlated with PDLIM2 levels (r2=0.2082; P=0.0328) in ovarian cancer specimens, suggesting a functional link between the two factors." (PMID 26593252, 2016). "M2 type macrophages recruitment was increased in the PDLIM2-repressed ovarian cancer tissue tumor microenvironment." (PMID 26593252, 2016). "Further functional analysis revealed PDLIM2 is epigenetically repressed in ovarian cancer development." (PMID 26593252, 2016). "Taken together, our data demonstrated PDLIM2 is repressed in ovarian cancer cells compared to normal tissue." (PMID 26593252, 2016). "Herein, we demonstrate PDLIM2 is decreased in both ovarian high-grade serous carcinoma and in various human ovarian cancer cell lines compared to normal ovarian tissues and human ovarian surface epithelial cells (HOSE)." (PMID 26593252, 2016). "Both OVCAR-3 cells and Caov-3 cells expressing PDLIM2 formed markedly fewer and smaller colonies compared to control, suggesting PDLIM2 suppresses ovarian cancer growth in vitro." (PMID 26593252, 2016). "To examine the role of NO synthesis in ovarian cancer growth in vivo, we treated PDLIM-2-repressed OVCAR-3 and Caov-3 cancer cells with NOS2 siRNA or control." (PMID 26593252, 2016). "Together, these data suggest promoter methylation is an important modulating factor in the expression of PDLIM2 in ovarian cancer." (PMID 26593252, 2016). "We next performed quantitative real-time PCR and immunoblotting to respectively determine PDLIM2 mRNA and protein levels in ovarian cancer cells and control HOSE cells." (PMID 26593252, 2016). "Immunohistochemistry analysis revealed NOS2 expression is significantly increased in PDLIM2-repressed ovarian cancer specimens." (PMID 26593252, 2016). "Functional analysis revealed PDLIM2 is epigenetically repressed by DNA methylation in ovarian cancer, which is conducive to cellular growth both in vivo and in vitro via NOS2-derived nitric oxide signaling." (PMID 26593252, 2016). "We demonstrate that PDLIM2 is decreased in both ovarian high-grade serous carcinoma and in various human ovarian cancer cell lines compared with normal ovary tissues and human ovarian surface epithelial cells (HOSE)." (PMID 26593252, 2016). "Further RT-PCR analysis revealed PDLIM2 mRNA level is significantly decreased in ovarian cancer tissues compared to normal ovary and fallopian tube tissues." (PMID 26593252, 2016). "In the current study, we demonstrate PDLIM2 expression was inhibited in both ovarian high-grade serous carcinoma and in several human ovarian cancer cell lines compared to normal ovarian tissues and human ovarian surface epithelial cells (HOSE)." (PMID 26593252, 2016). "Taken together, these data suggest PDLIM2 inhibition increases endogenous NO levels, with increased resultant ovarian cancer cell growth." (PMID 26593252, 2016).
ovarian carcinoma (continued). "Taken together, our results support the vital role NO signaling plays in PDLIM2-repressed ovarian cancer cell growth." (PMID 26593252, 2016). "To validate these observations in vivo, we separately incubated the control vector and PDLIM2-expressing ovarian cancer cells subcutaneously in nude mice." (PMID 26593252, 2016). "FlavoHb reduced NO synthesis in PDLIM2-repressed ovarian cancer cells, and inhibited both OVCAR-3 and Caov-3 cellular growth." (PMID 26593252, 2016). "Taken together, these data support PDLIM2-mediated suppression of ovarian cancer cell tumorigenicity." (PMID 26593252, 2016). "Both PDLIM2 mRNA levels and protein levels are significantly decreased in all ovarian cancer cell lines compared to control." (PMID 26593252, 2016). "Our study demonstrated NOS2 expression was increased in PDLIM2-repressed ovarian cancer cells, increasing intracellular NO synthesis in ovarian cancer cells." (PMID 26593252, 2016). "PDLIM2 inhibition promoted ovarian cancer growth both in vivo and in vitro via NOS2-derived nitric oxide signaling, which increased M2 type macrophage recruitment." (PMID 26593252, 2016). "We determined the mRNA and expression levels of these three NOS isoforms to identify which is responsible for increased NO synthesis in PDLIM2-repressed ovarian cancer cells." (PMID 26593252, 2016). "Inhibition of PDLIM2 promoted ovarian cancer growth both in vivo and in vitro via NOS2-derived nitric oxide signaling, leading to M2 type macrophages recruitment." (PMID 26593252, 2016). "PDLIM2 mRNA levels were decreased in ovarian cancer tissues compared to normal tissue in the Yoshihara and Hendrix datasets (P=1.22E-4 and P=1.87E-7, respectively)." (PMID 26593252, 2016). "We next investigated consequential downstream molecular events of PDLIM2 repression in ovarian cancer." (PMID 26593252, 2016). "Indeed, in vivo mouse experiments have proven that upregulation of PDLIM2 can inhibit ovarian cancer cell proliferation." (PMID 40476213, 2025). "Additionally, PDLIM2 attenuates the proliferation, migration, and invasion of ovarian cancer cells by inactivating the TGF-β/Smad pathway." (PMID 38880883, 2024). "The PDLIM2 promoter was hypermethylated in ovarian cancer cell lines compared to HOSE cells." (PMID 26593252, 2016). "Together, these results suggest PDLIM2 has an important role in ovarian cancer pathogenesis, and may be a promising therapeutic target in the treatment of ovarian cancer." (PMID 26593252, 2016). "To determine whether the PDLIM2 promoter is methylated in ovarian cancer cells, and whether 5-aza-dC–mediated restoration of PDLIM2 expression involves inhibition of PDLIM2 promoter methylation, we performed bisulfite genomic DNA sequencing." (PMID 26593252, 2016). "5-aza-dC treatment restored PDLIM2 expression in all studied ovarian cancer cell lines." (PMID 26593252, 2016). "Functional analysis revealed PDLIM2 is epigenetically repressed in ovarian cancer development." (PMID 26593252, 2016). "Both siPDLIM2-treated OVCAR-3 and Caov-3 ovarian cancer cells produced significantly more NO than control, suggesting PDLIM2 repression may increase NO synthesis." (PMID 26593252, 2016). "Further functional analysis revealed that PDLIM2 is epigenetically repressed in ovarian cancer development and inhibition of PDLIM2 promoted ovarian cancer growth both in vivo and in vitro via NOS2-derived nitric oxide signaling, leading to recruitment of M2 type macrophages." (PMID 26593252, 2016). "Our results support an important role of PDLIM2 in ovarian cancer pathogenesis, which might be a promising therapeutic target in the treatment of ovarian cancer." (PMID 26593252, 2016). "Given the critical role of NF-κB in ovarian cancer pathogenesis and the involvement of PDLIM2 in terminating NF-κB activation, we hypothesized PDLIM2 is involved in the ovarian cancer pathogenesis." (PMID 26593252, 2016).
ovarian carcinoma (continued). "Our current study demonstrated PDLIM2 is epigenetically repressed in ovarian cancer, and restoration of PDLIM2 significantly impaired ovarian cancer growth, suggesting an important role of PDLIM2 in ovarian cancer development." (PMID 26593252, 2016). "To characterize whether PDLIM2 suppression alters the tumor microenvironment, we analyzed the percentage of M2 type tumor macrophage cell infiltration in an ovarian cancer xenograft by immunohistochemistry." (PMID 26593252, 2016). "Although we demonstrated FlavoHb blocked NO availability and decreased ovarian cancer cell growth, the source of PDLIM2-repressed cell-derived NO remains unclear." (PMID 26593252, 2016). "However, PDLIM2-expressing ovarian cancer cells were significantly smaller than those formed by the vector-expressing cell lines." (PMID 26593252, 2016). "Therefore, PDLIM2 may also be a promising target for ovarian cancer treatment." (PMID 40476213, 2025). "To further investigate the effect of PDLIM2 expression in ovarian cancer, we performed a colony formation assay, employing OVCAR-3 and Caov-3 cells expressing PDLIM2 versus empty vector." (PMID 26593252, 2016). "We first compared the NO production capacity of PDLIM2-repressed OVCAR-3 and Caov-3 ovarian cancer cells by measuring nitrite (NO2-, a stable byproduct of NO) in culture medium." (PMID 26593252, 2016). "The mRNA level of PDLIM2 was significantly decreased in liver, lung, and ovary cancer compared to non-tumor tissues." (PMID 38880883, 2024). "Importantly, PDLIM2 overexpression in ovarian cancer cells inactivates the TGF-β/Smad pathway to reduce these malignancies, thereby suggesting a role for this pathway in ovarian cancer pathogenesis." (PMID 40476213, 2025). "Heretofore, whether PDLIM2 is similarly repressed in ovarian cancer has not been investigated." (PMID 26593252, 2016).
colon cancer (5 papers, 2011 to 2021). "PDLIM2 (PDZ and LIM domain 2) is downregulated in many types of NF-kB-associated tumors as leukemia, breast and colon cancer, supporting its role as a TSG in early phases of cancer development." (PMID 33672345, 2021). "PDLIM2 is repressed in a variety of tumors, including breast and colon cancer." (PMID 26593252, 2016).
autoimmune disease (4 papers, 2012 to 2025). A disorder resulting from loss of function or tissue destruction of an organ or multiple organs, arising from humoral or cellular immune responses of the individual to their own tissue constituents. "We therefore speculate that Fbxo16-deficiency in humans may cause autoimmune diseases and that the Fbxo16/PDLIM2-mediated pathway to terminate NF-κB activation could be the molecular tool for the development of the new therapy of these diseases." (PMID 40529355, 2025). "Thus, PDLIM2 negatively regulates immune responses in both innate and acquired immunity, preventing autoimmune diseases." (PMID 40529355, 2025). "Taken together, the PDLIM7/PDLIM2/p62-mediated degradation pathway to terminate p65 activation may prevent the onset of these autoimmune diseases and could be a novel molecular target for the treatment of autoimmune diseases." (PMID 32849529, 2020). "Additionally, it remains unknown whether PDLIM2 is involved in the pathogenesis of inflammatory and autoimmune diseases." (PMID 22731402, 2012). "PDLIM2 suppresses Th1 and Th17 cell differentiation through inhibition of STAT3/4 and RelA in autoimmune disease, indicating that PDLIM2 plays a crucial role in T cell-mediated immune responses." (PMID 35707002, 2022).
ulcerative colitis (4 papers, 2017 to 2026). An inflammatory bowel disease involving the mucosal surface of the large intestine and rectum. "In silico analysis of single cell RNA seq data sets from patients with ulcerative colitis and Crohn's disease demonstrated that although PDLIM2 was clearly expressed in normal human colonic epithelial enterocyte populations, its expression declined in both ulcerative colitis and Crohn's disease." (PMID 41743827, 2026). "miR-214 overexpression was also found to induce an inflammatory response in the ulcerative colitis experimental model by promoting NF-kB phosphorylation and subsequently IL6 expression through PTEN and PDZ-LIM domain-containing protein 2 (PDLIM2) inhibition." (PMID 36291876, 2022).
acute myeloid leukemia (3 papers, 2022 to 2024). Acute myeloid leukemia (AML) is a group of neoplasms arising from precursor cells committed to the myeloid cell-line differentiation. "PDLIM2 was only highly expressed in the tumor tissues of four cancer types (acute myeloid leukemia, low-grade glioma, pancreatic adenocarcinoma, and tenosynovial giant cell tumor)." (PMID 35121770, 2022).
colitis (3 papers, 2018 to 2026). Inflammation of the colon. "Interestingly, in +/+ mice, PDLIM2 expression was lost over the course of DSS-induced colitis." (PMID 41743827, 2026).
esophageal squamous cell carcinoma (3 papers, 2019 to 2024). Esophageal squamous cell carcinoma (ESCC) is a type of esophageal carcinoma (EC) that can affect any part of the esophagus, but is usually located in the upper or middle third. "In esophageal squamous cell carcinoma, PDLIM2 expression was significantly downregulated, and exon 7/8/9/10 of PDLIM2 was a novel valuable predictive characterization for esophageal cancer (EC) patients." (PMID 37894409, 2023).
gastric cancer (3 papers, 2016 to 2022). A primary or metastatic malignant neoplasm involving the stomach. "In contrast, patients with stage 3 gastric cancer showed lower PDLIM2 expression than patients with stage 2 disease." (PMID 35121770, 2022). "We also assessed cell growth, invasion, cell cycle progression, and tumorigenicity following PDLIM2 overexpression in NCI-N87 gastric cancer cells and obtained similar results to those described for MKN-45 cells." (PMID 26863570, 2016). "Together, these data indicated that OR3A4 upregulation contributes to metastasis and tumorigenesis in gastric cancer by regulating the activation of PDLIM2, MACC1, NTN4, and GNB2L1." (PMID 26863570, 2016). "Global microarray analysis combined with RT-PCR, RNA immunoprecipitation, and RNA pull-down analyses after OR3A4 transfection demonstrated that OR3A4 influenced biologic functions in gastric cancer cells via regulating the activation of PDLIM2, MACC1, NTN4, and GNB2L1." (PMID 26863570, 2016). "First, we screened several gastric cancer cell lines for PDLIM2 expression by western blotting." (PMID 26863570, 2016). "Therefore, OR3A4 overexpression may promote growth, invasion, metastasis, and tumorigenesis in gastric cancer in vitro and in vivo by upregulating MACC1 and GNB2L1 expression, and downregulating PDLIM2 and NTN4 expression." (PMID 26863570, 2016).
triple-negative breast carcinoma (3 papers, 2022 to 2025). An invasive breast carcinoma which is negative for expression of estrogen receptor (ER), progesterone receptor (PR), and human epidermal growth factor receptor 2 (HER2). "High PDLIM2 expression is associated with M2 macrophage infiltration, which is often considered a hallmark feature of invasive breast cancer, particularly triple-negative breast cancer." (PMID 40476213, 2025). "PDLIM2 is highly expressed in a subset of triple-negative breast cancer types, where it is only present in the cytoplasm and cell membranes, but not in the nucleus." (PMID 40476213, 2025). "Therefore, investigating the potential of targeted drugs to downregulate PDLIM2 expression, specifically in triple-negative breast cancer patients, may aid the development of future therapeutic strategies against this cancer subtype." (PMID 40476213, 2025). "PDLIM2 exhibits a dual role in cancer progression: it functions as a tumor suppressor in hormone-sensitive breast cancers and other malignancies, while paradoxically displaying elevated expression and pro-metastatic activity in triple-negative breast cancer (TNBC) and advanced metastatic tumors." (PMID 40476213, 2025). "In triple-negative breast cancer (TNBC), PDLIM2 is predominantly localized to the cytoplasm, and this spatial restriction positively correlates with β-catenin activation and adhesion signaling." (PMID 40476213, 2025).